MUC1 (mucin 1, cell surface associated)
Diseases named in the same sentence as MUC1 in open-access papers (continued):
Sharing a sentence is not in itself a finding about the gene and the disease.
breast carcinoma (continued). "A retrospective analysis was performed on the expression of MUC1, β-catenin and E-cadherin by immunohistochemistry on tumor tissues of a series of 112 breast cancer patients (total collective) treated in Munich between 2000 and 2002." (PMID 23890049, 2013). "Using netSAM, we identified six novel genes (TSPYL5, CD55, CCNE2, DCK, BBC3, and MUC1) as cancer biomarkers for predicting survival and metastasis in patients with breast cancer." (PMID 24073403, 2013). "miR-145 has been reported to suppress the invasion and metastasis of breast cancer cells by directly targeting MUC1 and that of esophageal cancer cells by deregulating FSCN1." (PMID 23390502, 2013). "In contrast to MUC1 antigen, autoantibodies to aberrantly glycosylated MUC1 are found more frequently and at higher levels in early-stage breast cancer patients." (PMID 23128437, 2013). "Towards the end of the 1980s, differences between the MUC1 expressed by healthy mammary cells and by breast cancer cells were observed using the monoclonal antibody, SM-3, specific for the MUC1 core protein stripped of sugars." (PMID 23509794, 2013). "siRNA-mediated silencing of CIN85 and/or MUC1 revealed that MUC1 enhances CIN85-dependent breast cancer cell migration and invasion in vitro." (PMID 24072600, 2013). "CTC were isolated using anti-EpCAM and anti-MUC1 coated magnetic beads from 2 × 5 ml of peripheral blood of 254 early and 51 metastatic breast cancer patients and 30 healthy individuals." (PMID 23497487, 2013). "MUC1 and CIN85 are both over-expressed in early as well as advanced clinical stages of breast cancer and co-localize on invadopodia-like structures implicated in cell invasion." (PMID 24072600, 2013). "Encouraging results were also obtained in a pilot phase III clinical trial where early-stage breast cancer patients (stage II) were immunized with oxidized-mannan MUC1." (PMID 23509794, 2013). "Autoantibody to aberrantly glycosylated MUC1, in early-stage breast cancer, is a typical example of such cases." (PMID 23128437, 2013). "Although CD44V4 is a major E-selectin ligand for breast cancer cells, there are other ligands such as MUC1 which play an active role in rolling and firm adhesion of breast cancer cells on inflamed endothelium, as reported in our recent study." (PMID 23372803, 2013). "MUC1 is regarded as a tumor antigen because it is aberrantly overexpressed in various cancers including lung cancer, and immunotherapy with anti-MUC1 antibodies showed substantial anticancer effect against prostate and breast cancers." (PMID 22457794, 2012). "Mucin 1 (MUC1) is a heterodimeric transmembrane glycoprotein that is overexpressed in about 90% of human breast cancers." (PMID 22792175, 2012). "A recent study concluded that full length MUC1 interacts with the transcription factor p65 and that this complex binds to cytokine promoter regions in the nucleus of breast cancer cells." (PMID 22905162, 2012). "Using A549 lung cancer and MCF-7 breast cancer cells as MUC1-expressing models, MA3 was found to preferentially bind to MUC1-positive but not MUC1-negative cells." (PMID 22384115, 2012). "The membrane bound mucin MUC1 is the most investigated mucin in breast cancer and is the most widely studied mucin for developing therapy to treat breast cancer." (PMID 23056409, 2012). "In cancerous tissue, MUC1 protein expression is aberrantly expressed on multiple cell surfaces on as much as 75% of human solid tumours and greater than 90% of human breast cancer and subsequent metastases." (PMID 23285151, 2012). "In a different study, Western blotting analysis of subcellular fractions from breast cancer tissue found MUC1 extracellular domain immunoreactivity in membrane, cytosol, and pellet/nuclear fractions." (PMID 22905162, 2012). "Unfortunately, as MUC1 changes its glycosylation pattern during neoplastic transformation, so it cannot be used as an early breast cancer biomarker." (PMID 22438764, 2012).
breast carcinoma (continued). "Carcinoma-associated MUC1 is known to be recognized by the immune system in cancer patients, and MUC1-specific cytotoxic T lymphocytes (CTLs) have been detected in colon, pancreatic, and breast carcinoma patients." (PMID 23028615, 2012). "Mucin1 (MUC1), a mucin and well-known marker of breast cancer, is an extended rod-like molecule which protrudes above the cell surface of epithelial cells." (PMID 22690157, 2012). "Although MUC1 expression correlates with high grade, metastasis potential, and poorer survival rate in breast cancer, the studies about MUC1 expression level in HCC are controversial." (PMID 22962849, 2012). "It should be noted that the MUC1 expression in these cells was diffuse and spread over the entire cell, one of the characteristics of mammary carcinoma cells in MMT mice." (PMID 22277639, 2012). "MUC1 has been proposed as a target for immunotherapy of breast cancer with some clinical trials exploring various MUC1-based vaccines having been conducted." (PMID 23285151, 2012). "MUC-1 is part of the family of membrane-bound mucins, large glycoproteins, and their expression is frequently elevated in breast cancer cells." (PMID 22873292, 2012). "In order to select for phage that specifically ‘home’ to MUC1-bearing tumours, the amplified phage from round two were injected into a tumour bearing nu/nu mouse xenografted with human breast cancer cell line MDA-MB-231." (PMID 23166757, 2012). "It has been reported that most IMPC are estrogen receptor (ER)-positive breast cancers displaying aberrant localization of the luminal glycoprotein mucin 1 (MUC1) at the stromal-basal surface of micropapillae, corresponding to an inversion of cell polarity." (PMID 22217342, 2012). "MUC1, a membrane glycoprotein of the apical cell borders, is aberrantly over-expressed by most human breast carcinomas." (PMID 22217342, 2012). "The most widely used serum marker in breast cancer diagnostics is CA 15-3, which is a soluble form of the mucin MUC1, which is in turn a marker of breast cancer." (PMID 22438764, 2012). "Our results further demonstrate that Rab31 and MUC1 are significantly co-expressed in ER+ breast cancers." (PMID 22792175, 2012). "Ongoing trials in our laboratory indicate that ddCTC are more frequently detected than CTC characterized by AdnaTestBreastCancerSelect and Detect kits (GA733-2, Muc-1 and Her-2) in primary breast cancer patients." (PMID 22443102, 2012). "VU4H5 is one of the most commonly used antibodies when targeting MUC1 and previous studies have shown a positive correlation for lymph node involvement and a higher staining intensity for higher grade breast cancer lesions." (PMID 23241107, 2012). "In IMPC at difference from other breast cancers, MUC1 is expressed on the basal surface of the cell clusters." (PMID 22217342, 2012). "MUC-1 is a membrane protein that is expressed in many epithelial cells but it is reported to be overexpressed in patients with breast cancer, inflammatory lung diseases, and HCC." (PMID 23162601, 2012). "In breast cancer, decreased expression of HMFG/MUC1 is associated with low overall patient survival, low stage of tumor cell differentiation, and increased incidence of distant metastasis." (PMID 23029547, 2012). "EDs, including NP, have been reported to induce the expression of pS2 and MUC1 in MCF-7 breast cancer cells." (PMID 22690157, 2012). "In this study, we investigate the role of MUC1 in breast cancer cell adhesion under flow with two cell lines: ZR-75-1 which is known to have a high metastatic potential, and MCF7 which is weakly metastatic." (PMID 22866263, 2012). "In breast cancer patients, the presence of circulating antibodies against MUC1 at the time of cancer diagnosis has been correlated with a favorable disease outcome." (PMID 24970145, 2012). "The ICC analysis of the MUC1 expression (using both antibodies) in canine mammary cancer cell lines showed staining patterns similar to those observed in humans." (PMID 22726603, 2012).
breast carcinoma (continued). "Previous study have well established that MCF-7 is a human breast cancer cell line that overexpresses MUC1 protein on its surface, and that HepG2 is a MUC1-negative human hepatic cancer cell line." (PMID 21912664, 2011). "IgG subclasses analyzed in MUC1 in 55 healthy controls and 26 breast cancer patients with high levels of abs to MUC1 were mostly IgG2, but also IgG1 and IgG3." (PMID 24212946, 2011). "Previous studies of MUC1 in breast carcinogenesis models show mixed results for different breast cancer cell lines, which reinforces the relevance of the molecular context on the MUC1-mediated cancer progression." (PMID 22073229, 2011). "Using MCF-7 breast cancer cell as a MUC1-overexpressing model, the MUC1 aptamer increased the uptake of nanoparticles into the target cells as measured by flow cytometry." (PMID 21912664, 2011). "In this study, we describe the selection of a human anti-MUC1 scFv antibody derived from a phage display immune antibody gene library of breast cancer patients repeatedly vaccinated with synthetic MUC1 glycopeptides." (PMID 21264246, 2011). "So far, human antibodies with good affinity and specificity for MUC1, a transmembrane protein overexpressed on breast cancers and ovarian carcinomas, and thus a promising target for therapy, were very difficult to generate." (PMID 21264246, 2011). "The mucin MUC1, a type I transmembrane glycoprotein, is overexpressed in breast cancer and has been correlated with increased metastasis." (PMID 21798038, 2011). "A pilot phase III was carried out in 31 Stage II breast cancer patients randomized to receive oxidized mannan-MUC1 or placebo." (PMID 24212946, 2011). "Although the ST glycoform is the main MUC1 glycoform found in sera of advanced breast cancer patients, fewer and weaker responses were seen to STMUC1." (PMID 21385452, 2011). "In 140 breast cancer patients, the presence of MUC1 immune complexes in serum samples obtained before primary treatment was inversely correlated to stage of disease at diagnosis." (PMID 24212946, 2011). "In examining the mechanism of action of sNDPK, it is interesting to note that sNDPK is thought to bind to the high molecular weight fragment of MUC-1, also shown to be present in the conditioned medium from breast cancer cells in culture." (PMID 21505453, 2011). "While some in-vitro studies showed that MUC1 overexpression promotes cellular invasion investigations of MUC1 expression of breast carcinomas have shown a better outcome for patients overexpressing MUC1." (PMID 21314937, 2011). "A human scFv antibody was isolated from an immune library derived from breast cancer patients immunised with MUC1." (PMID 21264246, 2011). "In contrast, IgG autoantibodies to defined MUC1 glycoforms were found in 31% of Stage I and II breast cancer patients." (PMID 21385452, 2011). "The most widely used serum marker in breast cancer diagnostics is CA 15-3, which detects soluble forms of the mucin MUC1." (PMID 22084684, 2011). "Given that MUC1 stabilizes ERα, stimulates ERα-mediated transcription, contribute to E2-mediated growth and survival of breast cancer cells, we asked if the effect of MUC-CD on mammary development is related to enhanced ER activity." (PMID 21533058, 2011). "Antibodies to aberrantly glycosylated MUC1 were measured using a microarray platform of 20mer MUC1 glycopeptides in 395 patients with early breast cancer." (PMID 24212946, 2011). "We analyzed the incidence of naturally occurring abs to MUC1 in 154 early breast cancer patients (52 Stage I and 102 Stage II) and related their presence in pretreatment serum to outcome of disease." (PMID 24212946, 2011).
breast carcinoma (continued). "The analysis of autoantibodies to MUC1 glycoforms demonstrated an autoantibody response in early stage breast cancer patients that is highly significantly related to age, emphasizing the importance of using age matched controls in screening." (PMID 21385452, 2011). "MUC1 is a promising target for breast cancer tumour therapy since it is overexpressed and underglycosylated on 90% of breast cancer and also on other cancer types." (PMID 21264246, 2011). "Peripheral B cells were isolated from six breast cancer patients vaccinated with synthetic MUC1 glycopeptide." (PMID 21264246, 2011). "Studies using mouse models have further established roles for MUC1 in the promotion and invasiveness of breast cancer." (PMID 21533058, 2011). "After a follow up of 8.5 years since the start of the trial the recurrence rate in the placebo group was 27%; none of the patients in the immunotherapy group had a recurrence (p = 0.029), suggesting that in early breast cancer MUC1 immunotherapy is beneficial." (PMID 24212946, 2011). "A humanized IgG1 MAb to MUC1, huHMFG1, and serum samples from breast cancer patients with high levels of MUC1 abs induced by vaccination with MUC1 peptides mediate ADCC in vitro." (PMID 24212946, 2011). "The mucin glycoprotein normally expressed at the apical border of epithelia (MUC1) is overexpressed by breast cancer cells that release/shed a high molecular weight fragment (Muc-1) in the conditioned medium from breast cancer cells in culture." (PMID 22091350, 2011). "MUC1 serum levels (CA 15.3 and CA 15.3-like assays) are used to monitor response to treatment in patients with breast cancer, and in the follow up to detect disease recurrence." (PMID 24212946, 2011). "Binding property of 10 ng of purified IgG from patient sera or huHMFG1 was assessed by FACS analysis using ZR-75-1, a breast cancer cell line that overexpresses MUC1." (PMID 24212946, 2011). "The authors examined by ELISA the presence of AAbs to five individual TAAs, PPIA, PRDX2, FKBP52, HSP-60, and MUC1, in sera from 60 breast carcinoma patients, 82 breast carcinoma in situ patients, and 93 healthy controls." (PMID 21423545, 2011). "At present, CA 15-3 (a soluble or secreted form of MUC1) has utility as a circulating marker for breast cancer." (PMID 22084684, 2011). "In breast cancer, miR-145 was identified to suppress cell invasion and metastasis by directly targeting MUC1." (PMID 21647377, 2011). "Collectively, our data indicate a critical role for MUC1-CD in the development of mammary gland preneoplasia and tumorigenesis, suggesting MUC1-CD as a potential target for the diagnosis and chemoprevention of human breast cancer." (PMID 21533058, 2011). "Presence and levels of abs to the MUC1 glycopeptides were significantly higher in breast cancer patients than in controls." (PMID 24212946, 2011). "We are unique in investigating the role of MUC1 in the motility of Luminal B breast cancer cell lines, focusing on the binding of MUC1 to ICAM-1." (PMID 21798038, 2011). "Unlike the low expression rate of antigens such as HER2 (20–25%), polymorphic epithelial mucin or MUC1 expression is considered to be universal (>90%) in breast cancer, as well as in other common epithelial cancers." (PMID 20160731, 2010). "Nonetheless, the most frequently encountered AAb response was directed against MUC1 protein, which was detected in 20/100 (20%) breast carcinoma patients compared to 3/100 (3%) healthy controls." (PMID 21113302, 2010). "We therefore undertook a Y2H screen to identify MAL2 binding partners expressed in human breast cancer tissue, which identified a number of novel putative binding proteins, including MUC1." (PMID 19175940, 2009). "Although MUC-1 is expressed at very low levels in normal tissues; it is overexpressed by most carcinomas, including breast cancers." (PMID 19635153, 2009).
breast carcinoma (continued). "It has been reported that a natural humoral immune response to MUC1 protein in early breast cancer patients results in improved disease-free survival." (PMID 19811637, 2009). "The intracellular localisation of MAL2 in breast cancer cells was determined using indirect immunofluorescence and confocal microscopy, and compared with that of MUC1." (PMID 19175940, 2009). "Breast cancer patients who demonstrate MUC1 overexpression in greater than 75% of tumor cells and aberrant subcellular localization (cytoplasmic and membranous) have significantly poorer disease-free and overall survival." (PMID 19811637, 2009). "The most common glycoprotein that can carry the STn glycan in breast carcinomas is the membrane-bound mucin known as MUC1." (PMID 19436292, 2009). "Further, another membrane-bound mucin MUC1 and rat Muc4 have also been shown to inhibit apoptosis induced by multiple insults in rat 3Y1 fibroblast cells and human melanoma and breast cancer cells, respectively." (PMID 19738614, 2009). "In the present study, we confirmed that this MUC-1 promoter version restricts viral protein synthesis, cytopathic effect, cell lysis, and infectious viral progeny production to MUC-1-positive breast cancer cells." (PMID 19635153, 2009). "Blood of 431 patients with primary breast cancer were analyzed for EpCAM, MUC1 and HER2 transcripts with the AdnaTest BreastCancerTM (AdnaGen AG, Germany)." (PMID 19664291, 2009). "The MUC1 transgenic mice were selected as a model as in breast cancer MUC1 is the major mucin that carries STn." (PMID 19436292, 2009). "Balb/c WT mice and MUC1 transgenic Balb/c mice that had been vaccinated with Theratope or controls were tumour challenged with mammary carcinoma cell line expressing MUC1 and ST6GalNAc 1 (E3-STn) or E3 that express human MUC1 without STn." (PMID 19436292, 2009). "We used a truncated version of the MUC-1 promoter that was previously shown to be specifically active in MUC-1-positive breast cancer cell lines." (PMID 19635153, 2009). "An antibody against MUC1 has the attraction in this context that its target is overexpressed in around 90% of human breast cancers." (PMID 19811637, 2009). "Taken together, these data demonstrate that replication of the Ad5AMUCH_RSV-NIS virus is stringently restricted to MUC-1-positive breast cancer cells, defining this virus as a conditionally-replicating adenovirus or CRAd." (PMID 19635153, 2009). "We therefore examined the distribution of MAL2 and MUC1 in Triton X-100-soluble and -insoluble fractions from breast carcinoma cell lines." (PMID 19175940, 2009). "Membrane-bound mucin MUC1 and rat Muc4 have been shown to inhibit apoptosis induced by multiple insults in rat 3Y1 fibroblast cells and human melanoma and breast cancer cells, respectively." (PMID 19738614, 2009). "In breast cancers, serum MUC1 measured by CA15-3 is a well established assay and has been shown to correlate with the clinical course." (PMID 20034397, 2009). "Taken together, these data suggest a role for MUC1 oncoprotein in estrogen-mediated cell growth and survival of breast cancer cells." (PMID 19811637, 2009). "Our findings support that in breast cancer there was a limited humoral immune response through Lewis y/IgM/CIC levels detection which correlated with MUC1/IgM/CIC." (PMID 19715603, 2009). "MUC1/IgM/CIC mean values obtained were the following: 0.320 ± 0.253 (mean ± SD) OD units for breast cancer samples; 0.453 ± 0.473 for benign disease and 0.406 ± 0.302 for normal samples." (PMID 19715603, 2009). "For this we developed a tumour cell line (E3STn) that expresses STn and MUC1 by the transfection of MUC1 and ST6GalNAc I, the sialyltransferase responsible for the formation of STn, into 410.4 mammary tumour cell line." (PMID 19436292, 2009). "We performed immunoprecipitation of MUC1 from breast cancer, benign and normal serum samples with HMFG1 MAb, directed against MUC1 peptide core (DTR) and isolated the glycoprotein." (PMID 19715603, 2009).